BARD1 (BRCA1 associated RING domain 1)
Diseases named in the same sentence as BARD1 in open-access papers (continued):
Sharing a sentence is not in itself a finding about the gene and the disease.
tumor (continued). "While promoter methylation of BRCA1 is frequently observed across cancers, BARD1 promoter methylation is comparatively rare, suggesting that preservation of BARD1 expression may contribute to its tumor suppressor function." (PMID 41009605, 2025). "As such, depending on cellular context, Sirtuins may support HR indirectly via stabilization of BARD1, or conversely, contribute to tumor progression and therapy resistance." (PMID 41009605, 2025). "BRCA2 mutations occur in 5–10% of prostate cases, and RAD51C/RAD51D, BRIP1, or BARD1 defects may broaden eligibility across tumor types." (PMID 40864792, 2025). "Notably, BARD1 expression inversely correlated with tumor weight, and BARD1 knockdown promoted angiogenic signaling pathways and therapeutic resistance." (PMID 41009605, 2025). "Despite the well-characterized roles of BARD1 in genome maintenance, BARD1 isoforms that lack the BRCA1-interacting domain or other critical regions may lose tumor-suppressive capabilities and instead contribute to tumorigenesis." (PMID 41009605, 2025). "BRCA1 is part of an obligate multifunctional heterodimer with BRCA1-associated RING domain 1 (BARD1), acting together as a tumor-suppressor E3 ubiquitin ligase involved in repairing double-strand DNA breaks through homologous recombination, maintaining genome stability." (PMID 39860065, 2025). "Genetic testing of the excised tumor revealed a MUTYH gene mutation and a BARD1 (BRCA1-associated RING domain 1) gene mutation of unknown significance." (PMID 39233942, 2024). "Interestingly, the BARD1 protein interacts with BRCA1 (BRCA1-BARD1) forming a tumor suppressor complex, which is an E3 ubiquitin ligase necessary for DNA double-strand breaks repair by RAD51-mediated homologous recombination." (PMID 38978731, 2024). "In particular, we observed reduced numbers of CD8+ T cells in PARPi-resistant, but not PARPi-sensitive, tumors from the Brca1- and Bard1-deficient tumor models." (PMID 38956205, 2024). "In addition, VEGFR2 inhibition in combination with talazoparib only modestly reduced tumor growth in the Brca1-def and Bard1-def models, whereas Flt1 inhibition in combination with talazoparib resulted in prominent tumor regression." (PMID 38956205, 2024). "Therefore, PARPi-resistant Brca1-def and Bard1-def tumor cells expressing either control (Con) or Flt1-specific guide RNA (Flt1i) were exposed to recombinant PGF in vitro." (PMID 38956205, 2024). "Interestingly, despite reduced angiogenesis, VEGFR2 inhibition in combination with talazoparib only modestly reduced tumor growth in the Brca1-def and Bard1-def models (EV2D), suggesting that other mechanisms are important for driving in-vivo PARPi resistance." (PMID 38956205, 2024). "Knock-in mice bearing the Ile26Ala BRCA1 RING domain mutation (which compromises its E3 ligase activity but retains the ability to form heterodimer with BARD1) did not display any overt developmental defects or increased predisposition for developing tumours." (PMID 38985307, 2024). "In contrast, BARD1 low expression was significantly associated with low tumor grade and non-papillary tumor shape in ERBB2-high patients." (PMID 37474724, 2023). "Additionally, we compared the expression levels of TIMD4 in HA cells and three GBM cell lines by cell line experiments and found that BARD1 was significantly highly expressed in tumor cells, especially SW1783 cells." (PMID 37853449, 2023). "Furthermore, BARD1 has been shown to behave as an oncogene, as reported in studies in which overexpression of spliced isoforms of BARD1 have been detected in tumor tissues." (PMID 36709314, 2023).
tumor (continued). "BARD1, a known tumor suppressor, is an obligatory binding partner of BRCA1." (PMID 36187937, 2022). "We observed that both BARD1- and PALB2-mutant cases had significantly higher median HRD scores than WT tumors (p = 0.023 and p = 0.041, respectively), consistent with alterations in PALB2 or BARD1 conferring tumor HR deficiency." (PMID 35768576, 2022). "Moreover, several published studies have designated p.Thr716Ala as deleterious, arguing that it abolishes binding to OLA1, a protein interacting in BRCA1-BARD1 complex, leading to the alteration of BARD1 tumor suppressor activity." (PMID 35595798, 2022). "BARD1 isoforms might be involved in tumor initiation and invasive progression and might represent a novel prognostic marker for NSCLC." (PMID 38091511, 2022). "Functionally, BARD1 protein acts as a tumor suppressor in BRCA1-dependent/independent pathways." (PMID 35650591, 2022). "One of these tumours had a concomitant alteration in BARD1, and a second in BRCA1 and RMI1." (PMID 34680387, 2021). "We were able to analyze tumor DNA of three men with BARD1 truncating mutation p.Q564X, three patients with a missense variant p.R658C, and three men with a synonymous change p.R659= for LOH at the BARD1 locus." (PMID 34771627, 2021). "Moreover, a negative correlation between increased RNF19A and decreased percentage of nuclear BARD1 was observed in tumor tissues." (PMID 34789768, 2021). "BRCA1-associated ring domain 1 (BARD1), nuclear partner of BRCA1, has been suggested as a potential HBOC risk gene, although its prevalence and penetrance are variable according to populations and type of tumor." (PMID 33498765, 2021). "The first, and most frequent, non-BRCA1/2 alteration seen was in BARD1, detected in four tumours." (PMID 34680387, 2021). "Indeed, we observed a negative correlation between RNF19A expression and nuclear/cytoplasm ratio of BARD1, which is lower in tumor tissues compared with adjacent tissues." (PMID 34789768, 2021). "While these findings support a role for the phospho-p50/BARD1-BRCT interaction in maintaining genome stability, whether phospho–protein binding is critical for tumor suppression by BARD1 is unclear." (PMID 33024116, 2020). "In this regard, it was recently reported that mice with mutations in the Bard1 phosphate-binding pocket were not tumor prone although they did demonstrate evidence of chromosome instability." (PMID 33024116, 2020). "We confirmed associations of BARD1 and PALB2 with the triple-negative subtype and ASTs, and found significant loss-of-function mutations on the wildtype allele of genes with germline mutations in the tumor samples." (PMID 32566746, 2020). "SNPs in the BARD1 gene have both oncogenic and tumor-suppressing roles." (PMID 32708251, 2020). "Current evidence suggests that protein interaction, pro-proliferative pattern, and localization of BARD1 isoforms are found to be highly different as compared to FL BARD1, indicating that isoforms obtained tumor-promoting functions, while losing tumor suppressor functions of FL BARD1." (PMID 30975222, 2019). "Because BARD1 may interact with other molecules implicated in genome integrity, a BRCA1-independent tumor suppressor functions for BARD1 have also been suggested." (PMID 31142030, 2019). "Furthermore, cancer-related BARD1 isoforms have been shown to be capable of antagonizing the functions of FL BARD1 tumor suppressor, resulting in genetic instability, DNA repair-deficiency, and loss of cell cycle regulation and increased cell proliferation." (PMID 30975222, 2019).
tumor (continued). "BARD1 may act as a tumor suppressor in the BRCA1-dependent pathways, which is associated with specific BRCA1/BARD1 heterodimer formation via N-terminal RING-finger domains." (PMID 31142030, 2019). "Deleterious mutations of BRCA1 often cause disrupted BARD1/BRCA1 interaction, suggesting that the formation of a stable BARD1/BRCA1 complex may be an essential aspect of BRCA1 tumor suppression." (PMID 29686231, 2018). "Furthermore, we establish the ubiquitin E3 ligase BARD1, a tumor suppressor and partner of BRCA1, as an indirect RNF4 target, regulated by PIAS1." (PMID 29180619, 2017). "Mutations in BARD1 gene may lack the RING domain that interacts with BRCA1, thereby affecting the sub-cellular localization and retention of BRCA1 and compromising tumor suppressor activity; these mechanisms may contribute to carcinogenesis." (PMID 28794477, 2017). "Whereas common and rare hereditable variants of BARD1 have been associated with cancer risk, recent high-throughput sequencing studies have found no frequently acquired somatic mutations in tumor tissues." (PMID 29292755, 2017). "BARD1 has tumor suppressor functions together with BRCA1 as E3 ubiquitin ligase." (PMID 28030839, 2017). "Due to the lack of the ring binding domain, BARD1β does not contain the binding site necessary for interaction with BRCA1 and may display oncogenic effect via affecting BARD1/BRCA1 tumor suppressor function either independent or dependent on FL BARD1 protein." (PMID 27197561, 2016). "PARN, a major deadenylase in mammalian cells, can potentially act as a tumor suppressor, given that it is activated by the tumor-suppressor BARD1 and it is involved in the degradation of IL-8, VEGF, c-jun, uPA, c-fos and TNF-alpha mRNAs, the levels of which are generally increased in cancers." (PMID 26541675, 2015). "It has been associated with the expression of cancer-related genes, it is activated by the tumor-suppressor BARD1 and it has been proposed that it could act as a tumor suppressor." (PMID 26541675, 2015). "Moreover, EWS protein has also been described to interact with BARD1, a putative tumor suppressor component of the BRCA1/BARD1 complex that performs essential DNA repair and recombination functions." (PMID 24082883, 2013). "These considerations would suggest that the BRCA1: BARD1 interaction may have another ubiquitin ligase-independent function that is essential for tumor suppression." (PMID 23802008, 2013). "In contrast, a subset of genes including tumor suppressors, such as BRCA1, BARD1 and BLM, were highly deregulated by loss of Spt6 but were only modestly affected or unaffected by loss of PAAF1, even though Spt6 level in these cells was significantly diminished." (PMID 22316138, 2012). "Therefore, targeted inhibition of HERC2 may enhance BARD1 stability and thereby promote tumor suppression." (PMID 41009605, 2025). "Beyond DNA methylation, other modifications could also influence BARD1’s tumor-suppressive role." (PMID 41009605, 2025). "Consequently, in the present study, the allele lacking full-length BARD1 expression due to the exon 3 deletion was likely to cause the loss or antagonism of tumor-suppressive functions, even in the presence of expressed isoforms." (PMID 38485918, 2024). "Also, BARD1 low was significantly associated with tumor grade (p = 0.04) and non-papillary tumor shape (p = 0.037)." (PMID 37474724, 2023). "Here, we identified for the first time an association between the variant allele of rs2070096 SNP in the BARD1 gene and a Miller–Payne tumor grade 5, that is, a pCR, not only in the whole patient cohort but also in the subgroup of 16 patients receiving TZ/PZ combo treatment." (PMID 36765720, 2023).
tumor (continued). "FL BARD1 has been reported to possess tumor suppressor properties, whereas BARD1 isoforms have been reported to be pro-oncogenic in many tumor types, antagonizing the functions of FL, indicating that there is a balance between the expression of oncogenic isoforms of BARD1 and FL BARD1." (PMID 35406624, 2022). "Therefore, we hypothesise that BARD1 alternative isoforms might play a role in most childhood tumours and as such, these cancers might share similar BARD1 profiles." (PMID 33530592, 2021). "Importantly, mutations in the BRCT domain of BARD1 did not lead to an increased tumour formation in mice, unlike BRCA1 BRCT mutations." (PMID 33755171, 2021). "Therefore, our hypothesis assumed that BARD1 taking part in early stage of development plays an essential role in the pathology of these specific neoplasms." (PMID 33530592, 2021). "Reduced expression of BARD1-FL (rs17489363) and formation of the oncogenic BARD1β isoform (rs6435862) increase susceptibility to NB and correlate with poor prognostic factors such as stage III and IV disease, older age at diagnosis and tumor originating in the adrenal gland." (PMID 32708251, 2020). "Although the molecular pathways activated or inhibited by the BARD1 oncogenic isoforms in NSCLC need to be further investigated, inhibition of these mutated proteins, especially isoforms β, κ, and π, may drastically inhibit tumor progression." (PMID 32708251, 2020). "Briefly, the expression of FL BARD1 (tumor suppressor role) is required for genomic stability and cell cycle control; in cancer initiation and progression the expression of BARD1 isoforms (oncogenes) antagonize FL BARD1 functions and permit uncontrolled proliferation." (PMID 29292755, 2017). "BARD1 mRNA expression level in HCC tissues was significantly associated with TNM stage (P < 0.001), BCLC stage (P = 0.006), hepatitis B surface antigen (HBsAg) status (P = 0.005), size of tumor (P = 0.004), serum AFP levels (P = 0.008), and serum aspartate aminotransferase (AST) levels (P = 0.003)." (PMID 28794477, 2017). "To explore the underlying mechanism by which BARD1 regulates the proliferation, invasion and migration of HCC cells, we further assessed its influence on the activity of Akt signaling pathway, which is well documented to be associated with tumor cell proliferation, invasion and migration." (PMID 28794477, 2017). "BRCA1 mRNA and protein in situ expression, as well as the amount of BRCA1 ligated to BARD1 in the tumor, lacked any associations with patient outcomes, likely due to high intratumoral heterogeneity, and thus could not be used for clinical purposes." (PMID 26490435, 2015). "In this review, we examine the multifaceted role of the DDR protein BARD1 in PDAC, with a focus on its complex regulatory mechanisms and the dual tumor-suppressive and oncogenic functions." (PMID 41009605, 2025). "The BARD1 and BRCA1 proteins form a heterodimer with multiple tumor-suppressing functions related to DNA repair and apoptosis." (PMID 40869938, 2025). "The inter-group expression difference analyses for tumor genes implied that APC, ATM, BARD1, BRAF, and BRCA1 gene expression varied among patients in these two groups." (PMID 38338834, 2024). "Of note, CD4+ helper T cells, B220+ B cells and F4/80+ macrophages also showed a trend towards increased tumor infiltration upon FLT1 blockade in the Brca1-def and Bard1-def models." (PMID 38956205, 2024). "BARD1 and BRCA1 form a heterodimer through the interaction of their RING-finger domains; this heterodimer plays crucial roles in several tumor-suppressive functions related to DNA repair and apoptosis." (PMID 38485918, 2024). "In the spatial transcriptome, it is clear that BARD1 expression is overall low, while CTSB and GSTP1 are mainly expressed in the core region of the tumor." (PMID 37727789, 2023).
tumor (continued). "The expression levels of BARD1 in HA cells and three GBM cell lines were initially compared through cell line experiments, revealing a notable upregulation of BARD1 in tumor cells." (PMID 37727789, 2023). "This was also accompanied by the restoration of HR capacity, G2/M cell cycle arrest upon DNA damage, formation of the BRCA1/BARD1 and BRCA1-A complex, critical to BRCA1 functions for tumor suppression." (PMID 35837282, 2022). "BARD1 and BRIP1 are both tumor suppressors, that act in the repair of double-stranded DNA damage, with proteins, interact with BRCA1." (PMID 34768979, 2021). "The interaction between RING domains within BARD1 and BRCA1 is critical for the tumour suppressive effects of the protein heterodimer, stimulating ubiquitin ligase activity." (PMID 33672422, 2021). "At the same time, the presence of cell migration inhibitors (APOE, AKT1, BARD1, GDF2) in exosomes from blood HFs accompanied by low stimulating effects on the migration velocity of tumor cells." (PMID 32218180, 2020). "As a result, we found two genes, BRIP1 and BARD1, that are involved in the HR pathway and show high expression only in the HRD tumor population." (PMID 32719318, 2020). "The BARD1/BRCA1 complex has known functions in homology-directed DNA repair (HDR), cell cycle regulation, and tumor suppression." (PMID 33024116, 2020). "Knocking down of BARD1-FL in SHSY5Y and SKNSH, two human NB cell lines, led to increased viability and invasion, which is consistent with the tumor suppression function of BARD1-FL in NB." (PMID 32708251, 2020). "The interaction between BARD1 and BRCA1 promotes tumor suppressor functions by acting in double-strand break repair and apoptosis initiation." (PMID 31036035, 2019). "Bound to BRCA1, BARD1 is essential for BRCA1’s E3 ubiquitin ligase and tumor suppressor activity in DNA repair and cell cycle control." (PMID 26415510, 2015). "Maintenance of expressed BRCA1 protein interaction with BARD1 was quantified, as a marker of BRCA1 functionality, and the tumor expression profiles of 27 microRNAs were determined." (PMID 26490435, 2015). "Several cancer-associated point mutations of the RING domain of BRCA1 (e.g., Cys61Gly and Cys64Gly) disrupted the BRCA1: BARD1 interaction, suggesting that this interaction contributes to BRCA1-dependent tumor suppression." (PMID 23802008, 2013). "Finally, the finding that the ubiquitin ligase function of the BRCA1: BARD1 is not required for HDR or tumor suppression in the mouse raises the additional question of why missense mutations of BRCA1 that disrupt the BRCA1: BARD1 interaction (e.g., Cys61Gly) lead to cancer in humans and in mice." (PMID 23802008, 2013). "Since PARPi resistance in the Brca1-def and Bard1-def models was more faithfully recapitulated in-vivo than in vitro (EV1), we hypothesized that signals from the tumor microenvironment are important for mediating PARPi resistance." (PMID 38956205, 2024). "Interestingly BARD1, CTSB, and GSTP1 were all highly expressed in tumor samples from the TCGA dataset." (PMID 37727789, 2023). "As recently reported, an NGS profiling including HR genes (BARD1, BRIP1, PALB2, RAD51C, and RAD51D) could improve the rate of tumor with HRD by 5–6%, identifying patients who may mostly benefit from PARPi therapy." (PMID 35406410, 2022). "In our cohort, we confirmed a higher expression of BARD1 β in the tumour but not in adjacent tissue; however, we did not observe any difference in BARD1 FL between cancer and non-neoplastic control." (PMID 33530592, 2021).